SPHK1 (sphingosine kinase 1)
Diseases named in the same sentence as SPHK1 in open-access papers (continued):
Sharing a sentence is not in itself a finding about the gene and the disease.
non-small cell lung carcinoma (13 papers, 2016 to 2025). A group of at least three distinct histological types of lung cancer, including non-small cell squamous cell carcinoma, adenocarcinoma, and large cell carcinoma. "LncRNA HULC via upregulation of the expression of sphingosine kinase 1 (SPHK1) leads to facilitation of non-small cell lung cancer cell proliferation and inhibits apoptosis." (PMID 35719962, 2022). "Statins partially inhibit TGF-β1-induced EMT in non-small cell lung cancer cells by decreasing the upregulation of sphingosine kinase 1 (SpHK1)." (PMID 34858839, 2021). "In the non-small-cell lung cancer cell line A549, inhibition of SPHK1 by its specific inhibitor SKI-II increases the sensitivity of the cells to paclitaxel." (PMID 33660008, 2021). "SPHK1 activated the PI3K/Akt/NF-kB pathway in non-small cell lung cancer." (PMID 39875359, 2025). "SPHK1 plays an important antiapoptotic role in non-small cell lung cancer in vivo." (PMID 36909198, 2023). "This review describes the mechanisms of targeted-drug resistance and newly identified non-small cell lung cancer targets (e.g., KRAS G12C, NGRs, DDRs, CLIP1-LTK, PELP1, STK11/LKB1, NFE2L2/KEAP1, RICTOR, PTEN, RASGRF1, LINE-1, and SphK1)." (PMID 36909198, 2023).
viral infection (13 papers, 2010 to 2023). "Cells overexpressing SphK1 are more susceptible to viral infection with increased virus replication and produce more virus proteins than the control cells." (PMID 33003377, 2020). "In this study, we focused on the regulation of Sphk1/2 gene expression, which has been shown to be affected by a viral infection in detail, in order to investigate S1P metabolism during influenza." (PMID 34635791, 2021). "Activation of SphK1/2 in response to a viral infection leads to clonal activation of CD8+ T cells." (PMID 38139132, 2023). "This suggests that the SphK1 protein may play different roles in different viral infections, or it may have multiple roles, and its role varies with the pathogenicity of the virus." (PMID 35891566, 2022). "Moreover, the activity of Sphk-1 has been shown to be increased in viral infections." (PMID 20634980, 2010).
Hypertension (12 papers, 2015 to 2024). The presence of chronic increased pressure in the systemic arterial system. "Inhibition of SphK1 has therapeutic significance because of the high residual risk of hypertension caused by vascular damage and cardiac dysfunction." (PMID 34737701, 2021). "TGM2 and SPHK1 have, e.g., both been associated with hypertension." (PMID 38791593, 2024). "Therefore, inhibition of SphK1 may be a promising target to solve the residual cardiovascular risk of hypertension." (PMID 34737701, 2021). "Pharmacological inhibition of SPHK1 in hypertension and cardiac hypertrophy resulted in reduced eNOS phosphorylation." (PMID 35127873, 2021). "SphK1 not only participates in the inflammatory process in hypertension, but also plays a regulatory role in the process of vascular damage." (PMID 34737701, 2021). "Recently, we have shown that during Ang II–dependent hypertension, the Sphingosine kinase 1 (Sphk1) was upregulated in the vasculature." (PMID 31321561, 2019). "Using Western blotting, flow cytometry and mass spectrometry approaches, we show that hypertension stimulates a sphingosine kinase 1 (SphK1)-dependent increase of cerebral S1P concentrations in a mouse model of angiotensin II (AngII)-induced hypertension." (PMID 30695999, 2019). "AngII-induced hypertension was blunted in Sphk1−/− mice (systolic BP 167 ± 4.2 vs. 180 ± 3.3 mmHg, p < 0.05), which was associated with decreased aortic and mesenteric vasoconstriction in hypertensive Sphk1−/− mice." (PMID 28276483, 2017). "While Sphk1 is important in mediating vasoconstriction in hypertension, Sphk1−/− mice were characterized by enhanced endothelial dysfunction, suggesting a local protective role of Sphk1 in the endothelium." (PMID 28276483, 2017). "While we have focused on Sphk1 as a key driver of several pathways modified in Ang II-induced hypertension, our study has identified several genes and can provide a reference for future in-depth studies." (PMID 28276483, 2017). "Sphk1 was identified as a member of numerous key biological pathways significantly altered in hypertension and its expression was induced in major arteries following Ang II stimulation in vivo." (PMID 28276483, 2017). "Further studies have identified that in opposition to overall protection from hypertension and decreased vascular contractility, endothelial dysfunction was significantly aggravated in Sphk1−/− mice." (PMID 28276483, 2017). "While numerous genes are altered during the development of Ang II-dependent hypertension, only Sphk1, Srpx and Mfap4 were common for different vascular areas studied." (PMID 28276483, 2017). "Thus, genetic deletion of SphK1 and pharmacological inhibition of SphK1 protected against hypoxia-induced hypertension." (PMID 35250621, 2022). "Therefore, SphK1 is up-regulated in inflammatory immune related-diseases, including hypertension, atherosclerosis, AD, RA and various types of cancers, and becomes a new target for the treatment of diseases." (PMID 34737701, 2021). "However, abnormal SphK1 expression and activity are found in various inflammatory and immune related-diseases, such as hypertension, atherosclerosis, Alzheimer’s disease, inflammatory bowel disease and rheumatoid arthritis." (PMID 34737701, 2021). "In addition, in AngII‐induced hypertension, inhibition of SphK1 attenuated the second stage of transmembrane Ca2+ influx." (PMID 32803879, 2020). "Modulation of the Sphk1 activity as well as targeting S1P receptors may provide a promising strategy for future studies aiming to prevent development of severe hypertension." (PMID 28276483, 2017). "Therefore we postulated that Sphk1 would play a critical role in the regulation of vascular function, BP increase, and consequently cardiac hypertrophy in hypertension." (PMID 28276483, 2017). "This may result in abnormally elevated level of superoxide anion production in Sphk1−/− mice in hypertension, yet our data only partially confirm this hypothesis." (PMID 28276483, 2017).
Hypertension (continued). "However, upon infusion of Ang II, Sphk1−/− mice developed significantly less severe Ang II-induced hypertension in vivo as compared to WT mice." (PMID 28276483, 2017). "Our data confirm that hypertension stimulates an SphK1-dependent increase of S1P concentrations in the brain, promoting the development of a distinct S1P gradient between brain tissue and circulating blood that in turn, might govern S1P1-guided T-cell chemotaxis to the hypertensive brain." (PMID 30695999, 2019). "Thus, vascular transcriptome analysis shows that S1P pathway is critical in the regulation of vascular function in AngII-induced hypertension, although Sphk1 may have opposing roles in the regulation of vasoconstriction and endothelium-dependent vasorelaxation." (PMID 28276483, 2017). "However, the role of SphK1/S1P pathway in renal injury in hypertension has not been reported." (PMID 32393187, 2020). "Together with the absence of CD3 signal in the brain of SphK1−/− and FTY-720-treated WT mice, comparable cerebral S1P1+ T-cell numbers between control and hypertensive WT mice strongly support a critical involvement of S1P-mediated T-cell infiltration into the brain during hypertension." (PMID 30695999, 2019).
Insulin resistance (12 papers, 2013 to 2024). Increased resistance towards insulin, that is, diminished effectiveness of insulin in reducing blood glucose levels. "Reduced plasma and adipose tissue S1P levels in SphK1−/− mice improved insulin resistance, which is associated with reducing adipocyte hypertrophy and inflammation in adipose tissue." (PMID 38256005, 2024). "Tipping the balance in favour of ceramide accumulation has been shown to cause insulin resistance whereas SphK1 prevents ceramide accumulation by promoting its metabolism to S1P and augmenting insulin action." (PMID 25866760, 2015). "Wang and colleagues demonstrated that SphK1 overexpression was associated with adipose proinflammatory responses and insulin resistance in diet-induced obese mice and obese diabetic humans." (PMID 25866760, 2015). "Interestingly, inactivation of SphK1 augmented the effect of PA induced insulin resistance in L6 myotubes, which was associated with further inhibition of insulin stimulated PKB and GSK3β phosphorylation, glucose uptake and the accumulation of sphingosine." (PMID 24376889, 2013). "Intraperitoneal injection of 5C (an SphK1 inhibitor) improved glucose tolerance, insulin resistance, and adipose tissue inflammation in HFD-fed mice." (PMID 38256005, 2024). "The SphK1 level was also elevated in obese, type 2 diabetic humans and in hepatic insulin resistance." (PMID 34943862, 2021). "In line with this, transgenic overexpression of SphK1 that promotes intramuscular ceramide conversion into S1P significantly improves muscle and whole-body insulin resistance in mice on an HFD for 6 weeks." (PMID 33633691, 2020). "Under a similar degree of whole-body insulin resistance, Sphk1-/- potentiates lipid-induced apoptosis of pancreatic β-cells, leading to the diabetic phenotype." (PMID 33633691, 2020). "Recently, two important studies on the role of SphK1 in adipose insulin resistance have been reported by Cowart laboratory." (PMID 33633691, 2020). "In hepatic insulin resistance, SphK2 has been illustrated as a metabolically protective factor, whereas the effects of SphK1 are controversial." (PMID 33633691, 2020). "By far, the majority of studies support a metabolically protective role of SphK1 in muscle insulin resistance." (PMID 33633691, 2020). "Overexpression of SphK1 prevents ceramide accumulation in myocytes ameliorates muscle insulin resistance in diet-induced obese mice." (PMID 33633691, 2020). "In muscle insulin resistance, the role of SphK1 is still under debate, while little is known about SphK2." (PMID 33633691, 2020). "In conclusion, we showed that, SPT inhibition is more effective in restoration of palmitate induced insulin resistance than SphK1 in L6 myocytes." (PMID 24376889, 2013). "The objective of this study was to examine the effects of short (2 h) and prolonged (18 h) inhibition of serine palmitoyltransferase (SPT) and sphingosine kinase 1 (SphK1) on palmitate (PA) induced insulin resistance in L6 myotubes." (PMID 24376889, 2013). "Although the results of our study cannot fully explain the exact mechanism by which the accumulation of CER impaired insulin pathway, both short- and long-terms inhibition of SphK1 intensified the palmitate induced insulin resistance in L6 myotubes." (PMID 24376889, 2013). "A recent review article showed that the role of SPHK1 in insulin resistance is controversial." (PMID 37626661, 2023). "Thus, the role of SphK1/S1P in muscle insulin resistance appears contradictory in the literature, which needs further clarification, especially by using myocyte-specific Sphk1-/- mice." (PMID 33633691, 2020). "Taken together, these results suggest that, under lipotoxic conditions, muscle SphK1 could play a protective role against the onset of insulin resistance." (PMID 32849282, 2020). "Importantly, overexpression of sphingosine kinase 1 leads to increased production of S1P and a reduction in insulin resistance in skeletal muscle after HFD compared to controls." (PMID 30828353, 2019).
Insulin resistance (continued). "Moreover, it has been shown that Sphk1 overexpression in muscle counteracts Cer levels and ameliorates insulin resistance in HFD mice corroborating the role of Sphk1 in cell survival." (PMID 28753653, 2017). "Furthermore, we found that inhibition of SphK1 increased level of sphingosine, which can contribute to insulin resistance." (PMID 24376889, 2013). "Moreover, the implications of SphK1 and SphK2 in insulin resistance have recently emerged." (PMID 34530846, 2021). "SphK1 transgenic mice fed an HFD showed increased SphK1 activity in skeletal muscle and insulin resistance." (PMID 34943862, 2021). "Myriocin is more effective in restoration of palmitate induced insulin resistance in L6 myocytes, despite of the time of SPT inhibition, comparing to SKII (a specific SphK1 inhibitor)." (PMID 24376889, 2013). "The SphK1/S1PR1/STAT3 axis may enhance and amplify insulin resistance." (PMID 34751249, 2021).
lymph node metastasis (12 papers, 2011 to 2025). "In oesophageal cancer, high SPHK1 protein was associated with increased risk of lymph node metastasis, and SPHK1 promoted cell migration, invasion and in vivo tumourigenesis and lung metastases." (PMID 40356021, 2025). "Some demonstrated that SPHK1 expression is associated with lymph node metastasis in human cancer by immunohistochemistry." (PMID 30018456, 2018). "This analysis also demonstrated that high SPHK1 expression in cervical cancer had the highest relative risk of recurrence (3.604), superior to the risk associated with lymph node metastasis (2.483) or lymphovascular invasion (2.716)." (PMID 26311741, 2015). "Of particular interest, the expression of SPHK1 was associated with well-known prognostic parameters including tumor size, invasion depth, lymph node metastasis, FIGO stage, and lymphovascular invasion." (PMID 26311741, 2015). "Univariate analysis for OS revealed that SPHK1 expression (p = 0.033), tumor size (p = 0.033), and lymph node metastasis (p = 0.008) were associated with OS." (PMID 26311741, 2015). "Available data also suggested that increased SphK1 markedly contributed to deep invasion, lymph node metastasis, and poor five-year overall survival, highlighting the exciting potential of SphK1 as a prognostic marker." (PMID 34831211, 2021). "In agreement, we reported that patients with lymph node metastases had significantly higher expression of activated SPHK1 in breast and gastric cancer patients." (PMID 30018456, 2018). "Univariate analysis for RFS showed that SPHK1 expression (p = 0.008), tumor size (p = 0.009), depth of invasion (p = 0.049), lymph node metastasis (p < 0.001), and lymphovascular invasion (p < 0.001) were significant predictors of poor RFS." (PMID 26311741, 2015). "SPHK1 expression was significantly associated with tumor size, invasion depth, FIGO stage, lymph node metastasis, and lymphovascular invasion." (PMID 26311741, 2015). "Statistical analysis indicated that in the esophageal carcinoma, the SPHK1 expression correlated with the depth of tumor invasion (P < 0.0001) and lymph node metastasis (P = 0.016)." (PMID 21936950, 2011). "Since BTC with lymph node metastasis have significantly higher expression of activated SPHK1, it is speculated that generated S1P contributes to lymphatic metastasis." (PMID 30018456, 2018). "Furthermore, in multivariate analysis, SPHK1 expression, lymph node metastasis, and lymphovascular invasion were identified as independent prognostic factors for RFS." (PMID 26311741, 2015). "SPHK1-positive FMT cells were found in lymphovascular invasion and lymph node metastasis FMT tissues." (PMID 31101115, 2019). "The recent study has also reported that Sphk1 is overexpressed in CRC cell lines besides the upregulation in CRC tissues, and the upregulation of Sphk1 is significantly correlated with lymph node metastasis, liver metastasis, and advanced TNM stage." (PMID 28991193, 2017).
multiple sclerosis (12 papers, 2014 to 2025). A progressive autoimmune disorder affecting the central nervous system resulting in demyelination. "FTY720 (Fingolimod), an immunomodulatory drug initially used for treating multiple sclerosis (MS), can influence sphingolipid metabolism and cell survival by inhibiting SPHK1 activity." (PMID 41304867, 2025). "A number of researchers have reported that the activation of the SphK1/S1P signaling pathway marks the occurrence of autoimmune diseases, and the up-regulation of SphK1 is related to the pathogenesis of multiple sclerosis." (PMID 35668943, 2022). "Furthermore, FTY-720, a sphingosine analog that inhibits SphK1, has been used clinically for the treatment of multiple sclerosis as an immune modulatory drug." (PMID 33134289, 2020). "It is noteworthy that FTY720 is an Sphk1 inhibitor that is approved by the United States Food and Drug Administration (US-FDA) for the treatment of multiple sclerosis." (PMID 36839802, 2023). "Importantly, a recent study has reported that upregulates the SphK1/S1P receptor signaling pathway may be a key factor of astrocytes mediated chronic inflammation in multiple sclerosis, and BBR ameliorated the severity of MS symptom in mouse model through inducing the increase in SphK1 and S1P." (PMID 33134289, 2020). "The role of the Sphk1/S1P/S1PR pathway in CNS injury and neuroinflammation is complex, and most of the current literature base has focused on neurodegenerative diseases such as multiple sclerosis, Alzheimer’s disease, and Parkinson’s disease." (PMID 33602274, 2021).
Alzheimer disease (11 papers, 2014 to 2025). A progressive, neurodegenerative disease characterized by loss of function and death of nerve cells in several areas of the brain leading to loss of cognitive function such as memory and language. "Up-regulation of SGPL1 and reduced expression of SPHK1, with a subsequent decrease in S1P, has been associated with neurodegeneration in Alzheimer’s disease and has also been described in animal models of Huntington’s disease (HD) as well as in post-mortem brain tissues from patients with HD." (PMID 36504680, 2022). "Here the authors examine how SphK1-mediates COX2 acetylation, and how this leads to increased secretion of SPMs from neurons in the context of Alzheimer’s disease models." (PMID 32398649, 2020). "Recently, in a murine model of Alzheimer’s disease, AT-LXA4 and RvE1 were endogenously produced via sphingosine kinase 1 (SphK1)-dependent acetylation of cyclooxygenase (COX)-2 and reduced disease pathology via enhancement of microglial phagocytosis." (PMID 30575798, 2018). "Interestingly, Alzheimer's disease is associated with SphK2, a key player of the UFIT pathway, that unlike SphK1, is upregulated in brain samples from patients with Alzheimer's disease, and as a result leads to S1P overproduction in neurons." (PMID 39877933, 2025).